FYB1 (FYN binding protein 1)
Description:
Acts as an adapter protein of the FYN and LCP2 signaling cascades in T-cells (By similarity). May play a role in linking T-cell signaling to remodeling of the actin cytoskeleton. Modulates the expression of IL2 (By similarity). Involved in platelet activation (By similarity). Prevents the degradation of SKAP1 and SKAP2. May be involved in high affinity immunoglobulin epsilon receptor signaling in mast cells (By similarity).
Synonyms: ADAP; FYB; SLAP130; SLAP-130; FYB-120/130; PRO0823; THC3
Tractability: Antibody: its Gene Ontology location is reachable by antibodies, with medium confidence; the Human Protein Atlas places it where antibodies can reach. PROTAC: ubiquitination databases record sites on it.
Gene: Protein-coding gene on chromosome 5 (39,105,252 to 39,274,528, reverse strand). Ensembl gene ENSG00000082074.
Subcellular location: Cytoplasm; Nucleus; Cell junction
Subcellular location (Human Protein Atlas): Plasma membrane; Nucleoplasm
Pathways (Reactome):
Cell-Cell communication: Signal regulatory protein family interactions
Immune System: Generation of second messenger molecules
Gene Ontology:
Molecular function: protein binding; signaling receptor binding; lipid binding
Biological process: immune response; integrin-mediated signaling pathway; protein localization to plasma membrane; T cell receptor signaling pathway
Cellular component: cytoplasm; actin cytoskeleton; anchoring junction; cytosol; nucleus; plasma membrane; protein-containing complex
Genetic constraint (gnomAD): Loss-of-function variants: 13 observed, 47.36 expected, observed/expected ratio (o/e) 0.27, 90% interval 0.18 to 0.44. The upper end of that interval is the gene's LOEUF score, 0.44, which puts it in group 1 of 6, group 1 being the genes least tolerant of losing a copy. Missense variants: 703 observed, 698.17 expected, observed/expected ratio (o/e) 1.01, 90% interval 0.95 to 1.07. Synonymous variants: 271 observed, 270.22 expected, observed/expected ratio (o/e) 1, 90% interval 0.91 to 1.11.
Gene-disease validity (ClinGen):
ClinGen rates the evidence that FYB1 causes each of these diseases.
thrombocytopenia 3 (autosomal recessive): Moderate.
Homologues: Orthologues: chimpanzee FYB1 (99% identical), macaque FYB1 (95% identical), dog FYB1 (86% identical), pig FYB1 (81% identical), guinea pig FYB1 (79% identical), rabbit FYB1 (79% identical), mouse Fyb1 (77% identical), rat Fyb1 (76% identical), tropical clawed frog fyb1 (42% identical), zebrafish fyb1b (32% identical), zebrafish fyb1a (17% identical). Paralogues in human: PRAM1 (19% identical), FYB2 (18% identical).
Diseases named in the same sentence as FYB1 in open-access papers:
FYB1 is named in the same sentence as 35 diseases in open-access papers, as found by Europe PMC text mining. Sharing a sentence is not in itself a finding about the gene and the disease. The quoted sentences say what the papers report.
Thrombocytopenia (5 papers, 2014 to 2024). A reduction in the number of circulating thrombocytes. "A mutation in the FYB1 gene has recently been identified to cause IT and although the exact mechanism of the mutation is still ambiguous, it has been suggested that thrombocytopenia arises from a reduction of mature MKs in the bone marrow and synthesis of small platelets." (PMID 31275945, 2019). "The FYB1 (chr1: 286,138,312–286,169,159 bp) gene was found to be related to thrombocytopenia, which is one of the typical symptoms of AD infection." (PMID 39071778, 2024).
acute myeloid leukaemia (2 papers, 2023 to 2025). "Moreover, it has been highlighted the FYB1/CAPG axis as a critical determinant of AML development, offering a promising therapeutic target for acute myeloid leukaemia." (PMID 40982354, 2025).
acral melanoma (1 paper, 2022). "When we performed the analysis separately for acral and mucosal melanomas, only a single additional candidate gene was flagged as significantly mutated, FYB1 in acral melanoma." (PMID 35706047, 2022).
tumor (8 papers, 2015 to 2025). "In vivo, downregulation of FYB1 significantly decreased the disease burden by suppressing tumor growth and improved survival rate." (PMID 37767202, 2023). "First, the CCLE database was used to examine FYB1 expression in tumor tissues." (PMID 38700746, 2025). "In addition, deficiency of FYB1 can enhance the cytotoxicity of CD8+ CTL and inhibit the expression of PD-1 in CD8+ effector T cells, thus significantly inhibiting tumor growth and enhancing antitumor immunity." (PMID 37767202, 2023). "FYB1 knockdown inhibited AML cell proliferation, promoted cell apoptosis, reduced cell adhesion capability and significantly reduced the tumor formation rate in mice." (PMID 38700746, 2025). "Belonging to the cytosolute linker protein group, FYB1 is essential for TCR signaling and extensively studied in terms of tumor pathogenesis and metastasis." (PMID 37767202, 2023). "Significantly higher transcript levels were observed in GBM tumours for AIDA (2.5-fold, p = 3.4 × 10−8), BNIP3L (1.2-fold, p = 5.5 × 10−6), CETN3 (1.8-fold, p = 1.7 × 10−7), FYB1 (1.8-fold, p = 7.25 × 10−9) and POLR2D (1.7-fold, p = 8.14 × 10−5)." (PMID 32635403, 2020). "Interestingly, AIDA, BNIP3L, CETN3, FYB1 and POLR2D were specific to GBM plasma-EV, and correspondingly, significantly higher gene expression levels were observed in GBM tumour tissue relative to healthy brain." (PMID 32635403, 2020).
cancer (6 papers, 2016 to 2025). A tumor composed of atypical neoplastic, often pleomorphic cells that invade other tissues. "Additionally, we compared the differences in FYB1 expression between normal and cancer cell lines and found that both mRNA and protein levels of FYB1 in cancer cell lines were higher than in CD34+ HSPC." (PMID 38700746, 2025). "FYB1 is involved in coagulation and T cell signaling and its role in cancer is unclear." (PMID 35706047, 2022). "As an SE-driven gene, overexpression of FYB1 was observed in T-ALL, according to the Cancer Cell Line Encyclopedia database." (PMID 37767202, 2023). "AIDA, CETN3, FYB1 and POLR2D are also unfavourable prognostic markers across multiple cancer types." (PMID 32635403, 2020).
FYB1 also shares sentences with these, for which no sentence is quoted: infection (6 papers); autoimmune disease (2); breast carcinoma (2); COVID-19 (2); diabetes (2); experimental autoimmune encephalomyelitis (2); Listeria monocytogenes Infection (2); viral infections (2); acute kidney injury (1); acute lymphoblastic leukemia (1); anemia (1); bacterial infection (1); bacterial sepsis (1); ductal carcinoma in situ (1); hematologic diseases (1); HIV-1 infection (1); immune thrombocytopenia (1); infiltrating ductal carcinoma (1); inflammation (1); leukemia (1); lymphoma (1); mastitis (1); melanoma (1); mucosal (1); multiple sclerosis (1); myelofibrosis (1); Sepsis (1); systemic lupus erythematosus (1); T cell lymphoma (1); thymoma (1).